ANXA2 (annexin A2)
Diseases named in the same sentence as ANXA2 in open-access papers (continued):
Sharing a sentence is not in itself a finding about the gene and the disease.
bladder cancer (continued). "The expression of ANXA1, ANXA2, ANXA3, ANXA5, ANXA6, ANXA8, and ANXA13 was closely related to basal-subtype bladder cancer, while the expression of ANXA4, ANXA9, ANXA10, and ANXA11 was closely related to luminal-subtype BC." (PMID 34484309, 2021). "We used TCGA data to find that in addition to ANXA1 and ANXA2, other ANXA family proteins (ANXA3, ANXA5, ANXA6, and ANXA9, which have not been studied) are also closely related to the prognosis of bladder cancer." (PMID 34484309, 2021). "In this study, we show ANXA2 and LIMK2 play oncogenic roles in mediation of the aggressiveness of bladder cancer cells." (PMID 31695759, 2019). "Therefore, we examined the secretion of AnxA2 in the condition media of RT4 and T24 bladder cancer cells." (PMID 36428758, 2022). "ANXA1, ANXA2, ANXA3, ANXA5, ANXA6, ANXA7, and ANXA9 had prognostic value in bladder cancer." (PMID 34484309, 2021). "Therefore, both ANXA2 and NPM may also take part in the mechanism of MDR in bladder cancer." (PMID 34048174, 2021).
colon cancer (13 papers, 2005 to 2023). "A new research found that ANXA2 mRNA is up-regulated at all stages of colon cancer and ANXA2 protein levels associate with high probability of invasion and distant metastasis." (PMID 32812032, 2020). "Several studies found Anxa2 overexpression in different types of tumors including colon cancer." (PMID 32812032, 2020). "Recently, ANXA2 is identified as a novel receptor for gastrin and progastrin (PG) peptides, which mediate the growth stimulatory effects of autocrine and exogenous gastrin and PG peptides on intestinal epithelial and colon cancer cells." (PMID 24591759, 2014). "However, the levels of the reduced form of ANXA2 were up-regulated in the gastric tumor and in four out of the six colon tumors compared to normal tissues." (PMID 22185818, 2011). "At the protein level, ANXA2 was upregulated in both mouse models of colon cancer." (PMID 20824133, 2010). "Furthermore, ANXA2 mediates the effects of gastrin/PG peptides that stimulate the growth of autocrine and exogenous gastrin and PG peptides on intestinal epithelial and colon cancer cells." (PMID 24591759, 2014). "We analyzed the distribution/localization of ANXA2 and PRDX2 in patient colon cancer tissue sections." (PMID 30959964, 2019). "Furthermore, expression patterns of ANXA2 and PRDX2 in colon cancer sections revealed that the distribution of these two proteins is highly distinct." (PMID 30959964, 2019).
lymph node metastasis (13 papers, 2012 to 2025). "ANXA2 has been reported to be associated with a variety of malignancies: A meta-analysis showed that ANXA2 over-expression was associated with tumor invasion, lymph node metastasis, overall survival, and poor prognosis." (PMID 33658625, 2021). "A recent study found that the membrane expression pattern of Annexin A2 was associated with high invasiveness and lymph node metastasis." (PMID 28423508, 2017). "Analysis of the TMA revealed that patients with cytoplasmic ANXA2 expression were more likely to have lymph node metastasis and vascular invasion." (PMID 41185558, 2025). "The high expression rate of ANXA2 in the lymph node metastasis group was 94.7 % (18/19), which was significantly higher than the negative lymph node metastasis group (58.0 % [29/50]; p < 0.05)." (PMID 26362938, 2015). "Annexin A2 down-regulation in these patients is prognostic and correlated with lymph node metastasis." (PMID 23519104, 2013). "Tumor size and location, differentiation, vessel invasion, and lymph node metastasis could affect ANXA2 overexpression." (PMID 32099594, 2019). "Similarly, another study has shown that increased expression of annexin A2 correlated with poor differentiation, late stage, and lymph node metastasis." (PMID 28423508, 2017). "The expression of ANXA2 and HE4 was significantly correlated with FIGO stage, degree of differentiation, myometrial invasion, and lymph node metastasis." (PMID 26362938, 2015).
triple-negative breast carcinoma (13 papers, 2018 to 2025). An invasive breast carcinoma which is negative for expression of estrogen receptor (ER), progesterone receptor (PR), and human epidermal growth factor receptor 2 (HER2). "Previous studies have shown Annexin A1 (AnxA1) and Annexin A2 (AnxA2) association with the aggressive behavior of Triple Negative Breast Cancer (TNBC)." (PMID 29416802, 2018). "ANXA2 was isolated from the serum of aggressive triple-negative breast cancer (TNBC) patients, and high levels of ANXA2 protein or mRNA were found to correlate with the degree of tumor malignancy." (PMID 39057791, 2024). "It has been reported that ANXA2 is more expressed in African American triple negative breast cancer (TNBC) patients compared to Caucasian TNBC patients, and high expression of ANXA2 is associated with worse survival." (PMID 37685859, 2023). "sEV-derived AnxA2 (sEV-AnxA2) protein is involved in the process of metastasis in triple-negative breast cancer (TNBC)." (PMID 36612209, 2022). "In contrast, in triple-negative breast cancer (TNBC), upregulated circEGFR binding to ANXA2 promotes ANXA2 translocation to the plasma membrane, leading to the release of TFEB from the ANXA2-TFEB complex and causing TFEB nuclear translocation." (PMID 40234383, 2025). "Additionally, Annexin A2 interacts with Gal-3 at membrane lattices, which is important for EGFR/MAPK signaling in the survival, growth and progression of triple-negative breast cancer." (PMID 32268913, 2020).
melanoma (12 papers, 2011 to 2025). A malignant, usually aggressive tumor composed of atypical, neoplastic melanocytes. "The level of the ANXA2 gene increased 2 fold in p16-deficient cells, and it is known that its expression is elevated in a wide range of cancers, including melanomas wherein p16 is usually inactive." (PMID 21799732, 2011). "Immunofluorescence analysis further revealed the colocalization of miR-150-3p and ANXA2 in melanoma cells." (PMID 40860143, 2025). "TEXs release from malignant melanoma cells have a high level of expression with annexin A1; however, the expression of annexin A2 was shown to be downregulated." (PMID 40305328, 2025). "In contrast, we combined ANXA2-enhanced miR-150-3p loading with iRGD peptide functionalization, achieving both precise melanoma targeting and potent therapeutic delivery." (PMID 40860143, 2025). "Conversely, CRISPR-mediated ANXA2 knockout (KO) in melanoma cells, achieved using ANXA2 sgRNA lentivirus transduction, substantially reduced ANXA2 expression, leading to elevated intracellular miR-150-3p levels." (PMID 40860143, 2025). "We next assessed the impact of ANXA2 KO on melanoma cell proliferation using a CCK-8 assay, which revealed significant suppression of A375 and A875 cells." (PMID 40860143, 2025). "qRT‒PCR analysis revealed increased ANXA2 mRNA levels in melanoma cell lines compared with normal melanocytes, whereas immunohistochemistry (IHC) confirmed increased ANXA2 protein expression in melanoma tissues compared with adjacent noncancerous tissues." (PMID 40860143, 2025). "Results: miR-150-3p was elevated in melanoma-derived EVs, and ANXA2 was identified as a key RNA-binding protein that selectively facilitated its loading into EVs." (PMID 40860143, 2025). "Further experiments demonstrated that miR-150-3p overexpression suppressed NF2 at both the mRNA and protein levels, whereas ANXA2 overexpression increased NF2 expression in melanoma cells." (PMID 40860143, 2025). "Annexin A2 is another representative protein with a connection to melanoma development and progression." (PMID 36834471, 2023). "The transcripts of 6 significantly changed proteins (VIM, DNM1, SMARCC2, CSDE1, EIF4A2 and ANXA2) have been previously identified as direct RNA targets of CSDE1 in human melanoma cells." (PMID 29129916, 2017). "SRC kinase has been shown to phosphorylate other members of the annexin family, in particular annexin 2 and we have previously shown that dasatinib treatment results in alterations in the phosphorylation status of ANXA1 and ANXA2 in WM-115 melanoma cells." (PMID 25594008, 2014). "In our study, we found that protein expression levels of annexin A1 were upregulated, whereas annexin A2 levels were downregulated in A375 melanoma exosomes." (PMID 23056502, 2012). "Annexin A1 and annexin A2 could be other biomarkers that are necessary for the invasion of melanoma by signaling proliferation." (PMID 40305328, 2025). "To explore the functional role of ANXA2, we overexpressed ANXA2 in melanoma cells." (PMID 40860143, 2025). "Although ANXA2 may have broader RNA-binding capacity, our findings highlight its specific and biologically relevant interaction with miR-150-3p in melanoma cells." (PMID 40860143, 2025). "However, our study identified ANXA2 as a novel regulator of miR-150-3p packaging, providing direct evidence that ANXA2 selectively enhances miR-150-3p encapsulation in melanoma-derived EVs." (PMID 40860143, 2025). "In melanoma S100A10 binds the CCR10 cytosolic tail, linking it to annexin A2 and regulating CCR10 surface expression; S100A10 knockdown increases CCR10 levels and disrupts annexin A2 association, underscoring its role in CCR10 localization and stability." (PMID 41050670, 2025). "We also used proteomic analysis and discovered differentially expressed melanoma exosomal proteins, including HAPLN1, GRP78, syntenin-1, annexin A1, and annexin A2." (PMID 23056502, 2012).
renal cell carcinoma (12 papers, 2008 to 2024). "Overexpression of annexin A2 has been found in renal cell cancer, where it is associated with tumour stage, invasive breast cancer and sarcomas, including both soft tissue sarcomas and osteosarcomas." (PMID 18071363, 2008). "Anxa2 overexpression has been observed in renal cell carcinoma, colorectal cancer, lung cancer and hepatocellular carcinoma." (PMID 37955107, 2023). "Among 20 different types of cancer, the protein level of ANXA2 was highest in renal cell carcinoma." (PMID 36713082, 2023). "This was consistent with the overproduction of Anxa2 protein in clear-cell renal cell carcinoma (RCC) and represents invasive and metastatic potential." (PMID 37955107, 2023). "Anxa2 siRNA could inhibit prostate cancer growth without detectable adverse effects.These strategies might be the focus for further investigations on pharmaceutical intervention in renal cell cancer." (PMID 37955107, 2023).
Sepsis (12 papers, 2015 to 2025). Sepsis is defined as life-threatening organ dysfunction caused by a dysregulated host response to infection. "To further understand whether AnxA2 has general immunity against a variety of pathogenic conditions, we employed the classical sepsis model in mice." (PMID 27389701, 2016). "Thus, AnxA2 deficiency-induced neutrophil infiltration may contribute to severe local and distant organ injury and higher mortality of sepsis mice." (PMID 27389701, 2016). "In cecal ligation and puncture (CLP) sepsis models, ANXA2 can suppress the inflammatory response in sepsis by regulating reactive oxygen species (ROS) and the IL-17 signaling pathway." (PMID 39057791, 2024). "This highlights the beneficial aspect of ANXA2 in inhibiting the inflammatory response during sepsis." (PMID 39057791, 2024). "In the cecal ligation model of sepsis, on the other hand, Anxa2−/− mice manifested a more severe sepsis phenotype with elevated IL-17 and increased ROS." (PMID 34202091, 2021). "In humans, lower levels of annexin A2 correlated with increased sepsis severity, and plasmin generation capacity is greatly reduced in septic patients compared to healthy controls." (PMID 34566657, 2021). "Studies in sepsis models have found that knockout mice that lack annexin A2 have more severe disease and decreased survival in polymicrobial sepsis, with significantly higher bacterial load, worse tissue integrity, and greater distant organ damage." (PMID 34566657, 2021). "In sepsis and inflammation, annexin A2 has different roles at different stages of the disease process." (PMID 34566657, 2021). "Here we identify a novel role for Annexin A2 (AnxA2), a multi-compartmental protein, in inhibiting pro-inflammatory response by regulating reactive oxygen species (ROS) and IL-17 signaling during sepsis." (PMID 27389701, 2016). "Together, our study shows that Anxa2 possesses a protective activity against sepsis by controlling NAPDH oxidase activation." (PMID 27389701, 2016). "Our overall data suggest that AnxA2 indeed plays a critical role in inhibiting heightened inflammatory response by regulation of ROS and IL-17A in this experimental sepsis." (PMID 27389701, 2016). "There is report that Sirt1 activation markedly alters transcription profiles and improves outcome in experimental sepsis, which is similar to what we observed with AnxA2." (PMID 27389701, 2016). "Our findings reveal a previously undemonstrated function for AnxA2 in inflammatory response in polymicrobial sepsis models via an AnxA2-ROS-IL-17 axis, providing insight into the regulation of pathophysiology of sepsis." (PMID 27389701, 2016). "In this study, we identify AnxA2 as a critical mediator in host defense against sepsis using a mouse CLP model." (PMID 27389701, 2016). "We determined the role of AnxA2 in sepsis based on cecal ligation and puncture (CLP)." (PMID 27389701, 2016). "To investigate whether AnxA2 generally affects ROS levels in other sepsis models, we employed bacterial infection models with E. coli and P. aeruginosa to study the relationship between ROS levels and IL-17A release." (PMID 27389701, 2016). "Collectively, our findings indicate that AnxA2 may represent a new layer of host defense systems against bacterial infection, thus a potential therapeutic target for sepsis." (PMID 27389701, 2016). "All these phenomena imply an important role of AnxA2 in host defense in CLP-induced sepsis." (PMID 27389701, 2016). "Importantly, AnxA2 functions as a putative ROS inhibitor in sepsis progression, and cysteine 9 of AnxA2 is the most important aa for oxidation regulation, helping the host copes with the disease." (PMID 27389701, 2016). "Moreover, ANXA2 could regulate the ROS production in the inflammatory response to polymicrobial sepsis." (PMID 36293376, 2022).
Sepsis (continued). "Previous research has found that in ANXA2 KO mice, faster bacterial growth and more severe tissue injury could induce a strong inflammatory response via an ANXA2-ROS-IL-17 axis during polymicrobial sepsis." (PMID 36159852, 2022). "Thus, AnxA2 may mitigate the severity of sepsis by modulating ROS and IL-17A levels." (PMID 27389701, 2016). "To determine whether these particles could be EVs produced by the CP, similar to what we described in sepsis, we analyzed the expression of several EV markers, namely ALIX, ANXA2, CD63, FLOT1 and RAB5, in brain samples from early stage AD mice compared to WT age-matched control mice." (PMID 34425919, 2021). "However, the relationship between AnxA2 and sepsis has not been clearly documented." (PMID 27389701, 2016).
atherosclerosis (11 papers, 2013 to 2025). A disease characterized by the build-up of fatty material and calcium deposition in the arterial wall resulting in partial or complete occlusion of the arterial lumen. "Conversely, AnxA2 deficiency suppressed atherogenic integrin α5 signaling induced by oscillary shear stress in a partial carotid ligation model of atherosclerosis in ApoE deficient mice." (PMID 36313572, 2022). "However, it is unknown the effect of AnxA2-deficiency in other cell types implicated in atherosclerosis." (PMID 36313572, 2022). "Within macrophages, proline/serine-rich coiled-coil protein 1 (PSRC1) interacts with annexin A2 (ANXA2) to delay the onset of atherosclerosis." (PMID 40895433, 2025). "For instance, HDAC9 promotes endothelial-to-mesenchymal transition (EndMT), accelerating atherosclerosis progression, and contributes to diabetic retinopathy by regulating ANXA2-mediated EndoMT." (PMID 41257548, 2025). "Despite the relationship of AnxA2 with angiogenesis and thrombosis, its relation with atherosclerosis is controversial." (PMID 36313572, 2022). "Otherwise, key genes have been emerged through our analysis related to the formation of the atherosclerosis plaque affected in DS, i.e. upregulation of ANXA2, although other factors like sex hormones can also be related to this feature." (PMID 23951402, 2013). "AnxA2 also participates in angiogenesis, a key contributor to atherosclerosis progression." (PMID 36313572, 2022). "Yet, although inhibition of plasmin generation has therapeutic potential in atherosclerosis, AnxA2 deficiency in apoE−/− mice did not reduce lesion development." (PMID 33810523, 2021). "Investigations into the roles of ANXA2 and SLC40A1 in the pathogenesis of atherosclerosis are notably scarce." (PMID 39364414, 2024). "Annexin A2 (ANXA2) complex, which facilitates plasmin production on the surface of endothelial cells, is involved in the pathogenesis of atherosclerosis." (PMID 37998729, 2023). "However, germline deletion of AnxA2 did not reduce atherosclerosis burden in ApoE-deficient mice." (PMID 36313572, 2022). "Among them, ANXA2, ApoA1, PGK1, CEBPB and MAP3K3 were related to atherosclerosis and cerebral inflammation." (PMID 34295249, 2021). "The ANXA2-R1 rs17845226 SNP has modest LD (r2 ≥ 0.4) with 34 SNPs, all located downstream of the ANXA2 gene-coding region in the long intergenic region between two genes, FOXB and ANXA2 on chromosome 15, and near the RORA and LIPC loci, which play roles in lipid metabolism and atherosclerosis." (PMID 28456096, 2017).
breast tumor (11 papers, 2013 to 2024). "It was found that Annexin A2 is highly expressed in breast tumor tissues and that FOXD1-dependent RalA-ANXA2-Src complex promotes circulating tumor cell formation in BC." (PMID 37189694, 2023). "Analysis of this data set also showed a significant down regulation in ANXA2 in breast tumor tissue compared to normal breast tissue (p < 0.0001, Mann–Whitney U)." (PMID 32629869, 2020). "We observed that serum AnxA2 concentration increases with the progression of the breast tumor grade." (PMID 33374917, 2020). "The expression of AnxA2 protein were analyzed in 67 breast tumor tissues and 9 normal breast tissues by immunohistochemistry (IHC) analysis." (PMID 33374917, 2020). "Rescue experiments performed in vitro and in vivo further demonstrated that LncCCAT1 facilitated breast tumor growth and metastasis through activation of the Wnt/β-catenin signaling pathway by binding with miR-204/211, miR-148a/152 and ANXA2." (PMID 31695775, 2019). "Our data provide evidence that MIEN1 interaction with AnxA2 enhances Y23 phosphorylation of AnxA2 and subsequent translocation of the protein to the cell surface leads to increased plasmin levels which support breast tumor cell motility." (PMID 26272794, 2015). "Our data show that the presence and interaction of both MIEN1 and AnxA2 in breast tumors are crucial drivers of cell motility." (PMID 26272794, 2015). "AnxA2 is overexpressed in tumor tissues of both invasive ductal mammary carcinoma and ductal carcinoma in situ compared to normal and hyperplastic ductal epithelial cells and ductal complexes, suggesting a crucial role of AnxA2 in breast tumor malignancy and invasiveness." (PMID 33374917, 2020). "The concentration of serum exo-AnxA2 in grade III breast patients was significantly higher than that of grade I and II breast tumor patients (P < 0.0001)." (PMID 31992335, 2020). "Taken together, these data indicate that co-expression of both AnxA2 and MIEN1 enhance plasmin generation and lead to an increase in breast tumor cell migration and invasion which in turn drive the metastatic process." (PMID 26272794, 2015).